CD4 (CD4 molecule)
Diseases named in the same sentence as CD4 in open-access papers (continued):
Sharing a sentence is not in itself a finding about the gene and the disease.
thyroid tumor (6 papers, 2015 to 2025). A benign or malignant neoplasm affecting the thyroid gland. "Macrophages and immature dendritic cells also accumulate in human thyroid tumors, both in the tumor stroma and at the advancing front, increased Tregs CD4+ CD25 infiltration in thyroid tissue has been correlated with an invasive phenotype." (PMID 37959281, 2023). "With the advantage of an integrated spatial transcriptome, we also discovered that thyroid tumour cells with low APOE expression interacted with DCs and CD4+ T cells via CD99‐regulated signalling but minimally interacted with the CD6 receptor." (PMID 39810624, 2025). "In this study we found only scarce CD4+ and CD19+ cells, reflecting a weak role of T-helpers and humoral immunity cells in thyroid tumors microenvironment." (PMID 39936166, 2025).
Trichinella spiralis infection (6 papers, 2011 to 2022). "Here, we used the murine model to examine the role of PD-1 in CD4+ T cells in the effects of Trichinella spiralis infection on collagen-induced arthritis (CIA)." (PMID 30093899, 2018). "A recent study suggests that neither the expression of this receptor on CD4+ T cells nor macrophages and neutrophils are required for protective immunity to Trichinella spiralis infection in mice." (PMID 21414188, 2011).
tuberculoid leprosy (6 papers, 2011 to 2023). A principal or polar form of leprosy in which the skin lesions are few and are sharply demarcated. "Furthermore, cytotoxic granulysin-expressing CD4+ T-cells have been isolated from skin lesions of tuberculoid leprosy patients." (PMID 21234358, 2011).
viral meningitis (6 papers, 2013 to 2024). Inflammation of the membranes surrounding the brain and spinal cord due to a viral infection. "Another highly relevant observation at that time was that alterations of the CD4/CD8 T cell ratio appeared to be diagnostically exploitable, as shifts towards CD8+ T cells supported the diagnosis of viral meningitis, whereas a shift towards CD4+ T cells supported the diagnosis of suspected MS." (PMID 35054246, 2021). "In contrast, the CD4/CD8 T cell ratio turned out to be relatively constant across several neurological diseases (range 1.8–8.0), which included but were not restricted to: bacterial and viral meningitis, LNB, MS, headache, and idiopathic intracranial hypertension." (PMID 35054246, 2021).
vitamin A deficiency (6 papers, 2012 to 2023). Deficiency of vitamin A due to malnutrition, malabsorption, or dietary lack. "It has been well-established that vitamin A deficiency in rats correlates with an impaired gut-homing ability in recently-activated mesenteric lymphocytes and a decreased number of CD4+ T cells in the ileum." (PMID 22443219, 2012). "Indeed, vitamin A deficiency has been shown to have a beneficial effect in a spontaneous model of intestinal inflammation by decreasing the homing of CD4+ T cells to the gut." (PMID 22443219, 2012). "In contrast to S. mansoni infection, we found that the numbers of GP61 and GP33 peptide-specific IFNγ- or TNFα-positive CD4+ or CD8+ T cells in the livers, spleens and MLN of LCMV-infected mice were unaffected by vitamin A deficiency." (PMID 22927819, 2012). "Baseline CCR9 expression on CD4+ T cells in naïve, uninfected mice was reduced as a result of vitamin A deficiency in the MLN and intestinal mucosa but not in the spleen, confirming previous reports that homeostatic RA synthesis is a selective function of APCs in the GALT." (PMID 22927819, 2012). "Concomitantly, the numbers of IFNγ+ and TNFα+ CD4+ T cells were not decreased in A− mice, indicating a selective defect in the TH2 response induced by vitamin A deficiency." (PMID 22927819, 2012).
vivax malaria (6 papers, 2015 to 2023). "In addition, future studies should address how vivax malaria chronically influences CD4 cells and how this is associated with HIV viral load dynamics." (PMID 33407474, 2021). "Considering the importance of CD4+ T cells in the protective immune response in vivax malaria, the objective of the present study was to verify possible mechanisms involved in lymphocytopaenia." (PMID 25559491, 2015). "During vivax malaria, apoptosis is moslty found in CD4+ T cells with a minor contribution of monocytes and non-CD4 T cells, which present significant frequency of cells in early apoptosis." (PMID 25559491, 2015). "A previous study showed that CD4+ T cells producing IL-17 were increased during vivax malaria." (PMID 28118834, 2017). "Although no studies have compared Plasmodium vivax infections with filarial co-infections it has been shown that the number of IL-17 producing CD4+ T cells is significantly increased during uncomplicated acute vivax malaria and directly correlated with elevated IFN-γ producing cells as well." (PMID 25889652, 2015).
Vogt-Koyanagi-Harada disease (6 papers, 2011 to 2025). A bilateral, chronic, diffuse granulomatous panuveitis typically characterized by serous retinal detachment and frequently associated with neurological (meningitis), auditory, and dermatological alterations. "describing clonal expansion of CD4 T cells in 4 patients with Vogt-Koyanagi-Harada’s disease (VKH), a granulomatous uveitis characterized by an immune response targeting melanocytes." (PMID 40060903, 2025). "In a subset of chronic uveitis patients (Vogt-Koyanagi-Harada disease), RNAseq analysis on the peripheral blood cells revealed that the gene for IL-7R is one of the highly expressed molecules in effector-memory CD4+ T cells." (PMID 40323267, 2025). "Further studies about the effect of both proteins on cytokine expression, apoptosis and chemotaxis of CD4+ T cells will contribute to our understanding about the mechanisms in the pathogenesis of VKH syndrome." (PMID 21297967, 2011). "Our results showed a significantly decreased expression of CD18 and AKNA in CD4+ T cells from patients with active VKH syndrome." (PMID 21297967, 2011). "In human systemic autoimmune diseases such as Vogt-Koyanagi-Harada syndrome, AKNA was found to be downregulated in CD4+ T-lymphocytes." (PMID 31357536, 2019). "Although the mechanisms involved in VKH syndrome are not fully elucidated, previous reports have showed that CD4+ T cells sensitive to melanocytes are responsible for the development of VKH syndrome." (PMID 21297967, 2011).
Achalasia (5 papers, 2015 to 2024). A disorder of esophageal motility characterized by the inability of the lower esophageal sphincter to relax during swallowing and by inadequate or lacking peristalsis in the lower half of the body of the esophagus. "Patients with achalasia had increased circulating CD4+ T cells, CD25- T cells, CD161+ T cells, FOXP3+ Tregs, IDO-expressing regulatory plasmacytoid dendritic cells (pDCregs), and IL-10-expressing regulatory B cells (Bregs) compared to healthy individuals." (PMID 38267468, 2024). "In the esophageal mucosa of achalasia patients, CD4+ T cells are shown to be a predominant immune cell population." (PMID 36450816, 2022). "Achalasia patients had significantly higher percentage of IFN-γ/CD4 T cells versus control group." (PMID 26078981, 2015). "We found TRM showed more expansions in achalasia than those in controls, especially in ZNF683+ CD8+ TRM and XCL1+ CD4+ TRM." (PMID 37542039, 2023). "Metascape analysis of marker genes of each TRM subcluster showed that ZNF683+ CD8+ TRM and XCL1+ CD4+ TRM, the most common types in achalasia, were enriched mainly in adaptive immune and lymphocyte activation." (PMID 37542039, 2023). "Among the TRM subclusters, XCL1+ CD4+ TRM (Th5) and ZNF683+ CD8+ TRM (Tc5), expanded remarkably in achalasia compared with controls." (PMID 37542039, 2023). "We show C1QC+ macrophages and tissue-resident memory T cells (TRM), especially ZNF683+ CD8+ TRM and XCL1+ CD4+ TRM, are significantly expanded and localized surrounding the myenteric plexus in the LES tissue of achalasia." (PMID 37542039, 2023). "We found TRM were increasingly infiltrated in the LES tissue in achalasia and mainly restricted to the area surrounding the myenteric plexus, especially ZNF683+ CD8+ TRM and XCL1+ CD4+ TRM." (PMID 37542039, 2023). "Nonetheless, levels of IFN-γ/CD4 T cells were higher in types II and III achalasia compared with type I achalasia." (PMID 26078981, 2015). "The aim of the study was to characterize the presence of diverse CD4 and CD8 T cell subsets and regulatory cells in peripheral blood and lower oesophageal sphincter (LES) from a young patient with BE/achalasia without treatment versus achalasia group." (PMID 27752370, 2016). "Although without a statistical difference, the proportions of CD4+ T cells and CD8+ T cells in LES tissue were slightly increased in achalasia compared with those in controls, while the proportion of each cell type in peripheral blood was quite similar between achalasia and controls." (PMID 37542039, 2023). "Although T cells widely infiltrate the myenteric plexus of LES in achalasia, it is not known whether CD8+ or CD4+ T cells predominate in LES tissue." (PMID 37542039, 2023).
adenomyosis (5 papers, 2021 to 2025). The growth of endometrial tissue inside the muscular wall of the uterine corpus. "By immunohistochemical staining, CD4, IL-17A, and IL-17R proteins were detected in both eutopic endometrium and adenomyosis at the level of EMI." (PMID 39456936, 2024). "Infiltration of CD4-positive immune cells was noted in both glandular and stromal tissues of the eutopic endometrium and adenomyosis." (PMID 39456936, 2024). "CD4, IL-17A, and IL-17R immunoreactive proteins were detected within both the eutopic endometrium and adenomyosis." (PMID 39456936, 2024). "In our study, the expression of GLT8D2 was downregulated in adenomyosis and positively correlated with the resting CD4 memory T-cell, resting NK cells and gamma-delta T-cell and negatively correlated with monocytes and CD8 T-cell." (PMID 36685847, 2022). "Considering the effect of B7-H2 on the differentiation of Th17 cells and Tregs from CD4+ T cells, it is reasonable to postulate that B7-H2 is involved in the pathogenesis of adenomyosis." (PMID 34289871, 2021). "Future studies should include FoxP3+ cell quantification to determine whether Treg deficiency contributes to the skewing toward CD4+ and CD8+ effector phenotypes observed in our adenomyosis model." (PMID 41298316, 2025). "In this study, we found that the expression of STEAP1 was positively correlated with the resting CD4 memory T-cell, M1 macrophages and gamma-delta T-cell and negatively correlated with monocytes and CD8 T-cell in adenomyosis." (PMID 36685847, 2022). "This occurrence was corroborated by immunohistochemical staining for CD4 (a marker of CD4+ T cells), CD8α (a marker of CD8+ T cells), and CD11c (a marker of DCs), which showed high protein levels at the invaginating site of adenomyosis." (PMID 40190183, 2025). "In addition, TOMM20 was positively correlated with the resting CD4 memory T-cell and negatively correlated with monocytes and CD8 T-cell in adenomyosis." (PMID 36685847, 2022).
adenopathies (5 papers, 2011 to 2024). "Three factors were independently associated with a lower risk of AFB negativity, namely adenopathies (OR = 0.4 [95%CI: 0.2–0.93]), cavitation (OR = 0.1 [95%CI: 0.03–0.6]) and CD4 fewer than 50 /mm3 (OR = 0.4 [95%CI:0.2–0.90])." (PMID 21731675, 2011). "In contrast, CD4 cell counts ≤50/mm3 (OR = 0.4 [95%CI:0.2–0.8]), adenopathies (OR = 0.54 [95%CI:0.3–1]), cavitation (OR = 0.16 [95%CI:0.04–0.7]) and retraction (OR = 0.10 [95%CI:0–0.6]) were associated with a lower risk of AFB negativity." (PMID 21731675, 2011).
allergic conjunctivitis (5 papers, 2013 to 2023). "This work aims to evaluate the potential involvement of TLR4/α-MSH in CD4+T cells and their functional impact in the cells of patients with perennial allergic conjunctivitis." (PMID 33114004, 2020). "In this work, we observed an increased expression of TLR4 in the CD4 T+ cells of patients with perennial allergic conjunctivitis (PAC)." (PMID 33114004, 2020). "We explore the possibility of inducing Treg CD4+CD25+FOXP3+ cells from the PBMC of patients with allergic conjunctivitis after specific allergen stimulation." (PMID 33114004, 2020). "Allergic conjunctivitis is initiated by the predominant activation of CD4+ T cells to environmental allergens, culminating in a Th2 response with generation of IgE antibodies." (PMID 24368924, 2013). "It is well known that in the chronic forms of allergic conjunctivitis CD4+ T cells are able to migrate to the ocular mucosa, maintaining the inflammatory process." (PMID 24368924, 2013). "We began by determining the percentage of CD25+ and CD4+CD25+ T cells in the peripheral blood of 14 patients with allergic conjunctivitis and 7 healthy controls." (PMID 24368924, 2013). "Thus, this study aimed to evaluate the potential involvement of TLR4/α-MSH in CD4-activated cells in patients with perennial allergic conjunctivitis." (PMID 33114004, 2020). "Further studies isolating CD4+TLR4+ cells from blood samples from allergic conjunctivitis patients and stimulating them with Der p are needed to determine if CD4+TLR4+ cells have a role in the induction of the IL-6 pro-inflammatory microenvironment and the inhibition of Treg cells." (PMID 33114004, 2020). "Remarkably, when we stimulated the PBMC of patients with perennial allergic conjunctivitis with Der p, we observed an increased TLR4 and CD69 in CD4+T cells, suggesting that allergen-specific stimulation also induces TLR4." (PMID 33114004, 2020). "Remarkably, when we stimulated PBMC in patients with perennial allergic conjunctivitis with Der p, we observed that TLR4 and CD69 were increased in CD4+T cells, suggesting that allergen-specific stimulation also induces TLR4." (PMID 33114004, 2020). "In experimental allergic conjunctivitis induced by short ragweed (SRW) pollen, typical allergic signs, stimulated IL-33/ST2 signaling and overproduced Th2 cytokine were observed in ocular surface, cervical lymph nodes and isolated CD4+ T cells of BALB/c mice." (PMID 27796360, 2016). "In order to explore whether CD4+TLR4+ cells were induced by Ag-specific stimulation (Der p) or by LPS stimulation, we obtained peripheral blood mononuclear cells (PBMC) from patients with perennial allergic conjunctivitis." (PMID 33114004, 2020). "In sum, the activation of CD4+TLR4+T cells by the antigen and TLR induces an inflammatory microenvironment characterized by TNF-α, IL-6, and IL-4, which favors a lack of immune regulation in perennial allergic conjunctivitis." (PMID 33114004, 2020).
allergic contact dermatitis (5 papers, 2021 to 2023). An inflammatory skin condition caused by an immune response to direct contact between the skin and an allergen. "The pathogenesis of allergic contact dermatitis involves selected T cell subpopulations: CD4, CD4CD25, CD4CD25high, and regulatory T cells defined as CD4CD25highCD127low." (PMID 36835932, 2023). "Langerhans cells are able to present antigens locally to activated CD4 T cells that infiltrate the site and through this mechanism are responsible for the induction of allergic contact dermatitis." (PMID 35328120, 2022). "Therefore, this study assessed the expression of iOPN in peripheral blood CD4 T lymphocytes in patients with allergic contact dermatitis." (PMID 36835932, 2023). "Finally, we demonstrated the presence of GLP-1R+CD4+ T cells in skin from patients with allergic contact dermatitis." (PMID 36010663, 2022). "Finally, to exclude that GLP-1R expression in T cells was just an in vitro phenomenon, we tested whether GLP-1R+CD4+ T cells could be detected in skin from patients with allergic contact dermatitis to nickel." (PMID 36010663, 2022). "The study aimed to determine CD4 T lymphocytes producing intracellular osteopontin and assess the T lymphocyte subsets CD4, CD4CD25, CD4CD25high, and CD4CD25highCD127low in the blood of patients with allergic contact dermatitis." (PMID 36835932, 2023). "In this study, we demonstrate that a sub-population of activated human T cells, and especially iTreg cells, express the GLP-1R, and that GLP-1R+CD4+ T cells are found in the dermis of both non-lesional and lesional skin from patients with allergic contact dermatitis." (PMID 36010663, 2022).
aortic aneurysm (5 papers, 2020 to 2023). A ruptured aneurysm located in the wall of the proximal portion of the descending aorta proceeding from the arch of the aorta. "In contrast, other groups have found that CD4+ T cells in aortic aneurysms are predominantly IL-4-producing Th2 cells." (PMID 35463756, 2022). "Inflammatory infiltrates of the aortic aneurysm wall were found to contain CD4+ T cells, including Th1, Th2, and Treg cells and CD8+ T cells, including both CD8+CD27− and CD8+CD28− cells." (PMID 33023269, 2020). "The percentage of CD4 + T cells, CD8 + T cells, B cells, monocytes, and macrophages increased in aortic aneurysms, while the proportion of VSMCs and fibroblasts significantly decreased." (PMID 35837612, 2022). "Biopsy samples of 11 patients with aortic aneurysm were immunomorphologically examined using antibodies to Lp(a) and CD3, as well as antibodies to CD4, CD8, and CD68." (PMID 33023269, 2020).
aphthous ulcers (5 papers, 2015 to 2024). "In clinical studies on treating recurrent aphthous ulcers, Gancao Xiexin decoction was found to regulate the imbalance of T lymphocyte subsets including the ratio of CD4+/CD8+ and the number of CD3+, CD4+, and CD8+." (PMID 34335839, 2021).
Arrhythmia (5 papers, 2018 to 2024). Any cardiac rhythm other than the normal sinus rhythm. "We could not, for instance, ascertain the extent at which concurrent medication use such as anti‐retroviral therapy (ART) impacted the incidence of arrhythmias, nor could we determine the relationship between disease severity (CD4 count or viral load) and arrhythmia risk." (PMID 33295667, 2021). "Multivariate model in our study showed a trend toward significant decrease of dysrhythmia with greater CD4 counts which was close to previous reports." (PMID 34328227, 2021). "Efavirenz regimen, mean heart rate, male gender and lower CD4 counts were independent predictors of total dysrhythmia." (PMID 34328227, 2021). "Mean heart rate, Efavirenz regimen, male gender, and CD4 count predicted total dysrhythmia." (PMID 34328227, 2021).
Ascites (5 papers, 2019 to 2025). Accumulation of fluid in the peritoneal cavity (between the layers of the peritoneum that lines the abdomen). "Cirrhotic patients with ascites are found to have lower numbers of naïve CD4+ and CD8+ T cells and higher numbers of activated CD4+ T cells in the peripheral blood, as well as increased production of IL-10 and TGFβ by T cells." (PMID 31627733, 2019). "From a global perspective, SHAP importance rankings placed two immune features in the top five: PD-1+CD8+ T cells (0.268) and PD-1+CD28+CD4+ T cells (0.264)-outperforming ascites volume (0.250) and far exceeding the modest importance of surgical method (0.021)." (PMID 41479903, 2025). "Human peripheral blood CD4+ and CD8+ T-cells were stimulated with anti-CD3/CD28-coupled beads and incubated with EVs isolated from 44 OvCa patients’ ascites." (PMID 31278254, 2019).
autoimmune vasculitis (5 papers, 2014 to 2025). An autoimmune form of vasculitis. "In human autoimmune vasculitis, TCF1+ stem-like CD4+ T cells have been identified within tertiary lymphoid structures surrounding the adventitial vasa vasora." (PMID 40634636, 2025). "However, a breach in this immune‐protection can lead to autoimmune vasculitis, as seen in GCA, where CD8+ T regulatory cells fail to control CD4+ T cells and macrophages, resulting in destructive granulomatous lesions." (PMID 39917373, 2025).